LDHB (lactate dehydrogenase B)
Diseases named in the same sentence as LDHB in open-access papers (continued):
Sharing a sentence is not in itself a finding about the gene and the disease.
tumor (continued). "In conclusion, our in vivo experiments have shown that silencing LDHB induces DNA damage in PM cancer cells, reduces tumor growth, and improves cisplatin therapy, indicating the potential of targeting LDHB for PM therapy." (PMID 40790017, 2025). "Functionally, LDHB knockdown significantly impairs cell growth, proliferation, invasion, and metastasis, ultimately arresting tumor growth both in vitro and in vivo." (PMID 40733189, 2025). "In an immune approach, pnp5a was involved in innate immunity, and the decrease in the expression of LDHB in humans was related to major tumor progression in various cancers." (PMID 41241706, 2025). "Dual targeting of LDHA and LDHB disrupted this metabolic interplay, reducing tumor growth and enhancing radiotherapy sensitivity in preclinical models." (PMID 41375052, 2025). "Accordingly, LDHB silencing disrupts autophagy, leads to lysosomal dysfunction, reduces tumor proliferation, and induces apoptosis via caspase-3 activation." (PMID 40733189, 2025). "The knockdown groups exhibited stronger tumor suppression than the LDHB overexpression group (p < 0.05)." (PMID 40977852, 2025). "Silencing ABCB1 or AKR1C3, or overexpressing LDHB, suppressed KIRC cell proliferation and migration in vitro; LDHB overexpression combined with sorafenib significantly reduced tumor growth in vivo." (PMID 40977852, 2025). "Metabolomics analysis revealed that LDHB silencing decreased nucleotide metabolism, particularly purine and pyrimidine biosynthesis, in tumor xenografts." (PMID 40158058, 2025). "A limitation of our study is that we evaluated the effect of LDHB silencing, both alone and in combination with cisplatin treatment, exclusively in a subcutaneous tumor model using immunocompromised hosts." (PMID 40790017, 2025). "Remarkably, combining cisplatin treatment with LDHB inhibition further decreased tumor volume compared to both single treatments." (PMID 40790017, 2025). "Summarizing our in vivo experiments, silencing or knockout of LDHB dramatically reduces tumor growth and increases the radiosensitivity of human xenografts and an immunocompetent orthotopic lung tumor model." (PMID 40090955, 2025). "Conversely, in the U251MG group, LDHB knockdown significantly decreased the tumor size, volume, and weight, whereas LDHA knockdown exerted the opposite effect." (PMID 39895794, 2025). "In detail, when combined with RT, shrinkage was observed in 9 out of 13 and only 1 out of 17 individual tumor nodules in the LDHB knockout versus wild-type background, respectively." (PMID 40090955, 2025). "Intriguingly, in U87MG group, LDHA knockdown led to decreased tumor growth, whereas LDHB knockdown exerted the opposite effect." (PMID 39895794, 2025). "Knocking out LDHB can inhibit tumour cell proliferation, telomerase activity and reduce telomere length in both in vivo and in vitro experiments." (PMID 38594465, 2024). "Collectively, these data demonstrate that GPER mediates glutamine biosynthesis and secretion in CAFs co‐cultured with TNBC cells by regulating GLUL expression and enhances glutamine uptake in tumour cells by regulating LDHB expression." (PMID 39690134, 2024). "In summary, this study identified a novel mechanism by which LDHB suppressed HCC progression via DNMT3A-induced hypermethylation of LDHB promoter and remodeling tumor immune environment." (PMID 38739169, 2024). "LDHB can also activate tumor cell lysosomes and perform autophagy through lysosomes, thereby regulating metabolism when tumor cells are under nutrition." (PMID 38594465, 2024). "Western blot analysis illustrated that LY2874455 treatment restrained FGF1, FGF2, STAT1, and LDHA levels but increased LDHB levels in tumor tissues." (PMID 38764020, 2024). "The promoter methylation level of LDHB was significantly lower in 4 tumor groups than in the normal group." (PMID 38291366, 2024).
tumor (continued). "To evaluate the potential role of LDHB in HCC, we first analyzed the LDHB mRNA expression in normal (adjacent) and HCC tissues in both TCGA database and GSE63898 datasets, and revealed that LDHB expression level was markedly decreased in the tumor tissues." (PMID 38739169, 2024). "The promoter methylation level of LDHB was significantly higher than that of the normal group in 3 tumor groups." (PMID 38291366, 2024). "After inoculation of WT mice with MC38 tumor cells, we injected cGAMP-treated WT BMDCs or LDHA/LDHB-deficient BMDCs into the tumor-bearing mice." (PMID 36821379, 2023). "Then, survival analysis indicates that a high expression of SLCA6A3, SLC16A1, and LDHA and a low expression of LDHB are recognized as a tumor progression promotor in some tumors." (PMID 37122693, 2023). "The down-regulation of LDHB skews TAMs to become a source of lactate and sterol/oxysterol for tumor cell proliferation." (PMID 37828561, 2023). "The lower LDHB enhanced lactagenesis and glycolysis in TAMs by tumor-derived miR-375, thereby enhancing TAMs cholesterol synthesis." (PMID 37828561, 2023). "Lactic acid is catalyzed by lactate dehydrogenase B (LDHB) to pyruvate, which is used by tumor cells through the TCA cycle." (PMID 36994237, 2023). "Further, cell line experiments showed a significant increase in LDHA expression and a significant decrease in LDHB expression in the tumor cell lines ACHN, 786-O, and OS-RC-2 relative to the human normal renal epithelial cell line HK2." (PMID 37795453, 2023). "Aurora-A phosphorylation on Ser 162 induces the augmented glycolytic activity of LDHB, leading to tumour growth." (PMID 37569364, 2023). "In particular, ablation of CD44 lowered the LDHA-to-LDHB ratio, promoting mitochondrial respiration, while overexpression of CD44 increased the LDHA-to-LDHB ratio, enhancing lactate glycolysis and the Warburg effect in tumor cells." (PMID 37894408, 2023). "In mouse cancer models, knockout of LDHA, LDHB, or knockout alone can inhibit tumor growth, highlighting their key role in tumor metabolism." (PMID 36875841, 2023). "We observed the expression level of LMRGs in different cell types, and we found that LDHA was mainly expressed in tumor cells and ACKR1+ endothelial, while LDHB was highly expressed in vSMC, tumor cells, mast cells, and CD8+ T cells." (PMID 37795453, 2023). "Public databases and WB analyses demonstrated higher LDHA and lower LDHB in ccRCC than in non-tumor tissues." (PMID 37547725, 2023). "LDHB, an enzyme involved in the conversion of lactate to pyruvate, has been found to play a crucial role in the energy metabolism of tumor cells." (PMID 37508430, 2023). "As LDHA and LDHB participate in tumor cell metabolism and adaptation to detrimental cellular conditions, these enzymes are reportedly involved in tumor pathogenesis and progression." (PMID 37547725, 2023). "Our findings suggest that GBM is similarly characterized by reduced LDHB expression, which is driven only in part by the hypoxic tumor micro-environment." (PMID 37107600, 2023). "Through AURKA-mediated phosphorylation of LDHB, glycolysis and biosynthesis were effectively promoted, thereby promoting tumor progression." (PMID 37333985, 2023). "Vascular endothelial growth factor (VEGF), the main inducer of neoangiogenesis by tumor cells, was quantified by ELISA, and an increase was only observed in LDHB KO cells (Fig EV3H), correlating with higher vascular coverage in LDHB KO tumor (Fig EV3I)." (PMID 36278433, 2022). "Our study pinpoints lactate as one of the main metabolic drivers, through both LDHA and LDHB activities, supporting tumor development and invasion in GB." (PMID 36278433, 2022). "It is interesting to further examine the relationship of LDHB expression, telomerase activity and cell senescence in tumor tissues, which fresh tumor tissues is required." (PMID 35669414, 2022).
tumor (continued). "miR-375-mediated downregulation of macrophage LDHB skewed TAMs to function as a lactate and sterol source for proliferation of tumor cells, emphasizing that the targeting cells should be strictly in LDHB inhibition treatment." (PMID 36407005, 2022). "To elucidate the impact of LDH expression on [1-13C]lactate labelling, we quantified the mRNA expression of LDHA and LDHB in both the tumour epithelial and stromal compartments." (PMID 35075123, 2022). "Inhibition of LDHB dramatically reduced the survival of tumor-initiating cells and sphere formation in vitro, which can be partially restored by nucleotide supplementation." (PMID 35877003, 2022). "The function of LDHB remains ambiguous in other tumor cells, such as triple-negative breast cancer (TNBC)." (PMID 36532721, 2022). "This approach enabled us to study T cells with higher and lower LDHB levels in the same tumor co-culture in parallel." (PMID 35682650, 2022). "Such as methylation of the LDHA promoter, hypermethylation of the LDHB promoter leads to suppression of LDHB expression and correlates with the metastatic potential of the tumor." (PMID 36551514, 2022). "However, the relative resistance to LDHB inhibition of the purified paraclonal culture was increased compared to the holoclonal culture, indicating that the holoclonal status, which is associated with increased tumor initiation capacity, is highly sensitive to LDHB inhibition." (PMID 35877003, 2022). "Tumor-derived miR-375 downregulates macrophage LDHB for microenvironment remodeling, leading to a higher level of glycolysis and proliferation of cancer cells." (PMID 36407005, 2022). "To the end, we investigated the anti-tumor activity of LDHB overexpressing T cells in an in vivo syngeneic tumor model." (PMID 35682650, 2022). "Here, we show that epithelial-like, tumor-initiating NSCLC cells feature oxidative phosphorylation (OXPHOS) phenotype that is regulated by LDHB-mediated lactate metabolism." (PMID 35877003, 2022). "As a consequence, we decided to use a human spheroid co-culture model to estimate the anti-tumor capacities of LDHB overexpressing cells." (PMID 35682650, 2022). "Examples of genes with more expression per cell in the erlotinib-treated group are PLAAT3, LCN2, CEBPD, and SAA1; conversely, LDHB is shown as an example for transcripts more abundant in control tumor cells." (PMID 36482068, 2022). "Compared to LDHA, LDHB is expressed only in certain types of tumors, and its role in tumor progression is not fully understood." (PMID 36551514, 2022). "Strikingly, LDHB-overexpressing cells preferentially migrated into HCT116 tumor spheroids and displayed higher expression of cytotoxic effector molecules." (PMID 35682650, 2022). "When feeling tumor-derived miR-375, TAMs downregulated the expression of LDHB and increased aerobic glycolysis and lactagenesis." (PMID 35911719, 2022). "LDHB provides sufficient energy for tumor-cell proliferative capacity while avoiding the accumulation of intercellular lactate." (PMID 36090994, 2022). "In the NSCLC cell lines A549, H358, H460, H838, and the primary culture PF139, silencing of LDHB dramatically reduced colony and sphere formation, which serves as an in vitro surrogate assay to assess tumor initiation." (PMID 35877003, 2022). "Our study revealed that LDHB has a vital role in tumorigenesis, both mouse xenograft tumor models and GEMMs." (PMID 35877003, 2022). "Together, these data indicate that LDHB overexpression can improve T cell infiltration and function in a suppressive tumor environment." (PMID 35682650, 2022). "This indicates that LDHA is an enhancer of tumor progression by fueling aerobic glycolysis and LDHB is a suppressor in glycolytic tumor cells." (PMID 36077431, 2022). "Statistical analysis of clinicopathological characteristics of LDHB disclosed that the expression levels of LDHB were related to the TNM stage of the tumor, recurrence, and survival in OS patients." (PMID 36059961, 2022).
tumor (continued). "Thus, in agreement with reducing the GLDC+ and ALDH+ subpopulations, LDHB silencing reduced the synthesis of pyrimidine and retinoic acid, both of which are critically associated with maintaining a stem-like state linked with increased tumor initiation capacity." (PMID 35877003, 2022). "This included measurement of the membrane transporters of pyruvate and lactate (MCT1, MCT4) and mRNA for the enzymatic subunits that catalyse the exchange between the two molecules (LDHA, LDHB), within tumour and stromal cells." (PMID 35075123, 2022). "Only a small but significant increase in mouse survival was observed in the LDHA KO group, and, surprisingly, a drastic decrease in survival in the LDHB KO group; the latter was most likely due to hemorrhages at the tumor site." (PMID 36278433, 2022). "Similar results have also been found from the two double KO cells in the LDHA/LDHB genes that completely block glycolytic pathways, but leave a low growth inhibitory effect in tumor cells, indicating cancer cell’s metabolic plasticity." (PMID 36077431, 2022). "It was shown that that inhibition of LDH, either pharmacologically (oxamate or GNE-R-140) or by gene knockout of LDHA and LDHB, significantly increases the radiosensitivity in tumor cells by a global impairment of the stress response." (PMID 35565435, 2022). "LDHA inhibitors are therapeutically a major target to inhibit tumor growth as known in lung cancer and a xenograft transplanted tumor, although LDHB is also a target." (PMID 36077431, 2022). "We observe similar changes in MCT4, LDHA, and LDHB between tumours with primary Gleason patterns 3 and 4 in an independent TCGA cohort." (PMID 35075123, 2022). "Even though the number of infiltrating MΦ was low, we observed a colocalization of CD163 and LDHB in decoy tumors, suggesting the presence of LDHB protein in TAMs under conditions when tumor cells are low in miR-375." (PMID 34158867, 2021). "A study found that LDHB is specifically upregulated in basal-like TNBC, and the loss of LDBH arrests tumor growth in vivo." (PMID 34917619, 2021). "Studies have found LDHA targeting tumor cells and LDHB targeting stromal cells influence tumor proliferation." (PMID 33718202, 2021). "Accordingly, in tumor cell antagomir treatment decreased miR-375 amounts in TAMs upon coculture and lowered LDHB expression, enhanced glycolytic activity as indicated by the enhanced mRNA expression of HK2 and MCT4, as well as enhanced lactate synthesis." (PMID 34158867, 2021). "Our results indicate that an inhibition of lactate dehydrogenase, either pharmacologically or by gene knockout of LDHA and LDHB, significantly increases the radiosensitivity in tumor cells by global impairing of the stress response." (PMID 34359663, 2021). "Here we provide evidence that tumor cell-derived miR-375 downregulates LDHB in macrophages, which is critical for their metabolic adaptation to become tumor supportive." (PMID 34158867, 2021). "In fact, LDHB was shown to control tumor progression and cancer cell proliferation through modulation of lysosome activity and autophagy." (PMID 34680521, 2021). "Evidently, miR-375 downregulates LDHB in MΦ, which stimulates their lactate formation and secretion to foster tumor cell proliferation." (PMID 34158867, 2021). "LDHB downregulation increase aerobic glycolysis and lactagenesis in TAMs in response to tumor-derived miR-375." (PMID 34158867, 2021). "In tumor cells, antagomir treatment significantly reduced the miR-375 amount in both cell lines, which was in line with increased LDHB and reduced PFKFB3 mRNA expression, while LDHA remained unaltered." (PMID 34158867, 2021). "Restoring of LDHB expression potentiated inhibitory effects of simvastatin on tumor cell proliferation." (PMID 34158867, 2021).
tumor (continued). "We concluded that downregulation of LDHB triggered lactate formation to stimulate TAM pro-tumor functions, while enhanced cholesterol biosynthesis did not alter the TAM phenotype." (PMID 34158867, 2021). "LDHB downregulation skewed TAMs to function as a lactate and sterol/oxysterol source for the proliferation of tumor cells." (PMID 34158867, 2021). "More specifically, knockout of both LDHA and LDHB was required to suppress glycolysis under hypoxic conditions and hence, curb tumor growth, but under normoxic conditions the tumor cell metabolism shifted to OXPHOS as an energy source." (PMID 33324565, 2020). "Malignant tumor tissue of premenopausal women showed significantly higher protein expression of LDHA concomitant with lower protein expression of LDHB." (PMID 33353120, 2020). "In young-PD patients ERG/MYC/NEDD4L/MAOA oncogene panel was found to be activated whereas in old-PD patients HLA-A/B/ANXA2/LDHB/ID4 tumor suppressor panel was down regulated." (PMID 33575208, 2020). "Oxidative tumor cells are located close to tumor blood vessels and predominantly oxidize lactate to pyruvate in a reaction catalyzed by LDHB, with the simultaneous output of NADH and H+." (PMID 33153193, 2020). "The role of LDHB in promoting lysosomal acidification required for autophagy-associated vesicle maturation and protease activation has been reported as a mechanism by which LDHB can promote tumor cell proliferation and survival in some cancer types." (PMID 33324565, 2020). "In order to confirm the effect of LDHB on tumour formation in vivo, we first established a stable NB4 and MOLM‐13 cell lines using shLDHB." (PMID 32391634, 2020). "Photographs and measured volumes of the tumours indicated that LDHB‐depleted cells grew much more slowly than control cells." (PMID 32391634, 2020). "Together, these data demonstrated that LDHB knockdown inhibited tumour growth and induced differentiation in vivo by blocking the Raf/MEK/ERK signalling pathway in AML." (PMID 32391634, 2020). "As mentioned, LDHA displayed similar (high) expression levels in all tumor cells, while the LDHB level varies among different tumor cells types." (PMID 31035592, 2019). "Here, the authors show that it modulates the activity of lactate dehydrogenase B, resulting in enhanced glycolysis, bio-synthesis and tumour growth." (PMID 31804482, 2019). "Additional confidently classified W-ex mutations from the cell line data that were noted to act in a similar manner as LDHB and have been shown to positively influence tumor progression are BCLAF1, JAK2, and KMT2D49–51." (PMID 31484939, 2019). "This review presents the latest progress made in this area on the roles of LDHA and LDHB in apoptosis and autophagy of tumor cells." (PMID 31035592, 2019). "Blocking S162 phosphorylation by expression of a LDHB-S162A mutant inhibited glycolysis and tumor growth in cancer cells and xenograft models." (PMID 31804482, 2019). "The information included in this review points to the legitimacy of modulating LDHA and/or LDHB to target tumor cells in the context of human and veterinary medicine." (PMID 31035592, 2019). "LDHB mRNA and protein levels are repressed followed by overexpression of miR-375 and increase after suppression of miR-375, which supports the notion that LDHB is a target of tumor cells miR-375." (PMID 31035592, 2019). "Increased concentration of lactate in the TME triggers MCT1, LDHB expression in the neighboring stromal cells such as hMSCs/CAFs which then take up the tumor-extruded lactate." (PMID 31146503, 2019). "Hypermethylation of the LDHB promoter and decreased gene expression are observed in various tumor cell lines." (PMID 30967137, 2019). "Experiments with PCa xenografts show that LDHA depletion compromises the tumor growth, while LDHB depletion promotes tumor growth." (PMID 30761180, 2019).